VHL (von Hippel-Lindau tumor suppressor)
Diseases named in the same sentence as VHL in open-access papers (continued):
Sharing a sentence is not in itself a finding about the gene and the disease.
renal cell carcinoma (continued). "However, unlike in renal cell carcinoma, only 28 out of 369 cases (7.6%) displayed VHL mRNA downregulation." (PMID 35664333, 2022). "Interestingly, chromosome 11 loss in VHL-related tumors is specific to PGL/PCC and has not been shown in VHL-related renal cell carcinomas." (PMID 28099933, 2017). "To test this hypothesis, in addition to the renal cell carcinoma cell line RCC4, we used another renal cancer cell line, UOK121, in which VHL is epigenetically silenced, along with the RCC4 + VHL and UOK121 + VHL cell lines, which were stably transfected with functional VHL." (PMID 27460078, 2016). "RCC, especially its most common form, clear cell renal cell carcinoma (ccRCC), the VEGF pathway plays a crucial role due to the inactivation of the von Hippel-Lindau (VHL) tumor suppressor gene." (PMID 38629578, 2024). "Based on these results, we can speculate that VHL, at least at some points during tumor progression, might be regulated by miR-92a-3p in PTC as well, since the possibility of their direct interaction was demonstrated in renal cell carcinoma and epithelial ovarian carcinoma cells." (PMID 36036061, 2023). "Although the cause of renal cell carcinoma (RCC) remains unknown in most cases, the RCC TME among patients undergoing dialysis and those with Von Hippel–Lindau (VHL) gene abnormality has been considered to differ significantly." (PMID 32707869, 2020). "In renal cell carcinoma (RCC), HERV-E is selectively expressed in cancer cells lacking the VHL tumor suppressor, and peptides derived from its envelope protein have been shown to bind HLA-A*0201 and stimulate patient-derived CD8+ T cells." (PMID 34925363, 2021). "Data from studies using paired isogenic renal cell carcinomas with non-functional (VHL null; HIF-1α/2αhigh) and functional VHL protein (VHL restored; HIF-1α/2αlow), along with siRNA of HIF, allowed us to firmly implicate the role of HIF in downregulating MHC class I expression." (PMID 29155844, 2017).
clear cell renal cell carcinoma (363 papers, 1998 to 2026). "Clear cell renal cell carcinoma (ccRCC) is characterized by the loss of the von Hippel-Lindau (VHL) gene, leading to constitutive activation of hypoxia-inducible transcription factors (HIFs) and metabolic reprogramming toward aerobic glycolysis." (PMID 41857011, 2026). "Clear-cell renal cell carcinoma (ccRCC) is characterised by constitutive activation of hypoxia-inducible factors (HIFs) following VHL loss, which contributes to tumour progression and therapeutic resistance." (PMID 42074150, 2026). "Clear cell renal cell carcinoma (ccRCC) is characterized by disrupted lipid metabolism, traditionally attributed to VHL mutations and HIF stabilization." (PMID 41565622, 2026). "The development of clear cell renal cell carcinoma (ccRCC) is marked by mutations to Von Hippel Lindau gene, resulting in reduced expression or inactive forms of VHL protein and aberrant Hif-1⍺ expression under normoxia as well as hypoxia." (PMID 40238833, 2025). "Clear cell renal cell carcinoma (ccRCC) is strongly aetiologically associated with von Hippel‒Lindau (VHL) tumour suppressor gene mutations, which result in constitutive activation of hypoxia-inducible factors and pathological angiogenesis." (PMID 40435846, 2025). "Clear cell renal cell carcinoma (ccRCC), accounting for 80–90% of renal malignancies, is frequently driven by VHL inactivation—either through mutation or promoter hypermethylation—resulting in constitutive HIF2α activation and pseudohypoxic signaling." (PMID 41226668, 2025). "VHL missense mutations define an aggressive subtype of clear cell renal cell carcinoma (ccRCC) with poorer survival outcomes." (PMID 40909272, 2025). "Clear cell renal cell carcinoma (ccRCC) is tightly associated with VHL (von Hippel-Lindau tumor suppressor) mutation and dysregulated angiogenesis." (PMID 39477683, 2025). "Clear cell renal cell carcinoma (ccRCC) is characterized by near ubiquitous loss of VHL followed by mutations in epigenetic regulators PBRM1, SETD2, and BAP1." (PMID 39874221, 2025). "VHL inactivation by mutation or transcriptional silencing is observed in most sporadic cases of clear cell renal cell carcinoma (ccRCC)." (PMID 40240354, 2025). "We also compared the HIF2α protein levels between doxycycline induced iHIF2α LAN-1 cells and human endothelial cells (HUVEC) and in VHL deficient clear cell renal cell carcinoma (ccRCC) cells (786-O)." (PMID 41118218, 2025). "The von Hippel–Lindau (VHL) gene is frequently mutated in clear cell renal cell carcinoma (ccRCC) which results in stabilization of hypoxia-inducible factor (HIF)." (PMID 40736709, 2025). "A common gene mutation in clear cell renal carcinoma is the loss of function of the von Hippel-Lindau (VHL) gene, which is associated with NF-kB overexpression." (PMID 40005133, 2025). "Clear cell renal cell carcinoma often has mutations in VHL tumour suppressor genes, leading to upregulation of the HIF family." (PMID 40169553, 2025). "Currently, there is only one drug that directly targets the HIFα subunit in clinical use: the HIF-2 dimerization inhibitor belzutifan, which is used to treat HIF-2 prevalent VHL-deficient clear cell renal cell carcinoma." (PMID 40918648, 2025). "The majority of clear cell renal cell carcinoma (ccRCC) tumors arise from sustained inactivating mutations in the VHL gene." (PMID 39948060, 2025). "Clear-cell renal cell carcinoma (ccRCC) is associated with the mutated von Hippel–Lindau (VHL) gene leading to the activation of hypoxia-inducible factor 1A (HIF1A) and subsequent overexpression of erythropoietin (EPO)." (PMID 40332447, 2025). "These nuances of crosstalk highlight the importance of modeling the biophysical environments and genetic interactions that compound the loss of VHL, a tumor suppressor pivotal to clear cell renal cell carcinoma (ccRCC) tumorigenesis." (PMID 40238833, 2025).
clear cell renal cell carcinoma (continued). "Clear cell renal cell carcinoma exhibits certain molecular genetic characteristics, and molecular genetics can detect genes such as Von Hippel-Lindau (VHL), folliculin (FLCN), and BRCA1-associated protein-1(BPA1)." (PMID 40395268, 2025). "The binding of VHL to elongin C is blocked in VHL gene-deficient clear cell renal cell carcinoma (ccRCC), which results in reduced ubiquitination and proteasomal degradation of HIF1-α." (PMID 40225869, 2025). "Inactivation of VHL is common in clear cell renal cell carcinoma (ccRCC), and it has been reported that up to 90% of ccRCC have loss-of-function mutations in VHL." (PMID 39605894, 2024). "Tumor mutation burden (TMB) and VHL mutation play a crucial role in the management of patients with clear cell renal cell carcinoma (ccRCC), but the time‐consuming and expensive high‐throughput sequencing methods severely limit their clinical applicability." (PMID 39166457, 2024). "In this review, we examine existing radiogenomics literature in clear cell renal cell carcinoma (ccRCC), the predominant renal cancer, and von Hippel–Lindau (VHL) gene mutation, the most frequent genetic mutation in ccRCC." (PMID 38666933, 2024). "The von Hippel-Lindau tumor suppressor gene (VHL) is mutated in up to 90% of clear cell renal cell carcinoma (ccRCC) cases, thus playing a key role in ccRCC pathogenesis." (PMID 38304003, 2024). "Renal cancer is the most common adult genitourinary cancer, approximately 85% of which is accounted for by the clear cell renal cell carcinoma (ccRCC) subtype characterized by VHL loss." (PMID 38618952, 2024). "Clear cell renal cell carcinoma (ccRCC) is characterized by Von Hippel Lindau (VHL) gene loss of function mutation, which leads to the accumulation of hypoxia-inducible factor 2α (HIF2α)." (PMID 39406703, 2024). "Tumor mutation burden (TMB) and VHL mutation play a crucial role in the management of patients with clear cell renal cell carcinoma (ccRCC), such as guiding adjuvant chemotherapy and improving clinical outcomes." (PMID 39166457, 2024). "Clear cell renal cell carcinoma (ccRCC) is the most common subtype of human kidney cancer, characterized by the loss of the Von Hippel-Lindau tumor suppressor (VHL)." (PMID 39279883, 2024). "Familial cases of clear-cell renal carcinoma are mostly associated with VHL germline pathogenic or potentially pathogenic variants." (PMID 39336594, 2024). "Germline pathogenic variants in VHL predispose patients to tumors including clear cell renal cell carcinoma (ccRCC) and pheochromocytoma, and somatic VHL mutations are frequently observed in sporadic renal cancer." (PMID 38969834, 2024). "The VHL tumor suppressor gene was initially discovered as a germline mutation in patients at risk for clear cell renal cell carcinoma (ccRCC), which constitutes approximately 85% of all kidney cancers." (PMID 38618952, 2024). "As a paradigm to address this, we longitudinally studied the changes induced by loss of the tumor suppressor gene von Hippel Lindau (VHL), which ultimately drives clear cell renal cell carcinoma." (PMID 38502859, 2024). "Loss of chromosome 3p and loss of heterogeneity of the von Hippel-Lindau (VHL) gene are common characteristics of clear cell renal cell carcinoma (ccRCC)." (PMID 39592433, 2024). "Clear cell renal cell carcinoma (ccRCC), comprising approximately 85% of primary renal cancers, is characterized by the loss of the von Hippel-Lindau (VHL) tumor suppressor gene." (PMID 38618953, 2024). "von Hippel-Lindau (VHL), known as a tumor suppressor gene, is frequently mutated in clear cell renal cell carcinoma (ccRCC)." (PMID 39050705, 2024). "The Von Hippel–Lindau (VHL) protein, which is frequently mutated in clear-cell renal cell carcinoma (ccRCC), is a master regulator of hypoxia-inducible factor (HIF) that is involved in oxidative stresses." (PMID 38360997, 2024).
clear cell renal cell carcinoma (continued). "A previous article described a study on clear cell renal cell carcinoma (ccRCC), focusing on how the loss of the von Hippel–Lindau (VHL) gene in cancer cells impacts the tumor microenvironment (TME), particularly immune cell infiltration and behavior." (PMID 39451551, 2024). "Conversely, the VHL substrate transcription factor ZHX2 has been identified as an oncogenic driver in VHL-deficient clear cell renal cell carcinoma (ccRCC)." (PMID 39850947, 2024). "Clear cell renal cell carcinoma (ccRCC) is an aggressive cancer driven by VHL loss and aberrant HIF-2α signaling." (PMID 38941296, 2024). "Clear cell renal cell carcinoma (ccRCC) is chiefly associated with the loss of the von Hippel-Lindau (VHL) gene, encoding a component of the E3 ubiquitin ligase complex." (PMID 38618953, 2024). "Clear cell renal cell carcinoma (ccRCC) progression, which is the most common form of kidney cancer, is associated with the loss of the Von Hippel-Lindau (VHL) gene in renal epithelium." (PMID 36831657, 2023). "Loss of function of the von Hippel-Lindau (VHL) tumor suppressor gene is a hallmark of clear cell renal cell carcinoma (ccRCC)." (PMID 37069149, 2023). "VHL gene mutations were found in tumors associated with VHL syndrome as well in some sporadic tumors, such as clear-cell renal carcinomas, hemangioblastomas, and sporadic pheochromocytomaarise harbor VHL gene mutations." (PMID 36036061, 2023). "von Hippel-Lindau (VHL) disease, due to mutations of the tumor suppressor VHL gene, is a rare hereditary syndrome with a high risk of developing clear cell renal cell carcinoma (ccRCC)." (PMID 38201462, 2023). "Unfortunately, he developed hypoxic respiratory failure, and only posthumously did WES/WTS reveal pathogenic variants in BAP1 and VHL, consistent with clear cell renal cell carcinoma (ccRCC)." (PMID 37844295, 2023). "There are many mutated genes have been reported to be associated with clear cell renal cell carcinoma, including von Hippel Lindau(VHL), Polybromo 1 (PBRM1), BRCA associated protein 1 (BAP1) and SET domain containing 2 (SETD2)." (PMID 37679715, 2023). "In the current era of tumor genome sequencing, single amino acid missense variants in the von Hippel–Lindau (VHL) tumor suppressor gene are frequently identified in clear cell renal carcinoma (ccRCC)." (PMID 37762376, 2023). "The VHL (von Hippel–Lindau) tumor suppressor gene is the most frequently mutated gene in clear cell renal cell carcinoma (ccRCC) followed by PBRM1, BAP1 and SETD2." (PMID 37762376, 2023). "Von Hippel–Lindau (VHL) loss is the hallmark event characterizing the clear cell renal cancer subtype (ccRCC)." (PMID 37489462, 2023). "We attempted to analyze the consequences of the VHL-C162F mutation in ccRCCs using the clear-cell renal carcinoma 786-0 cells (VHL−/−) transfected with either empty (EV), WT VHL, or VHL-C162F encoding vectors." (PMID 38201462, 2023). "von Hippel-Lindau (VHL) mutations play a critical role in clear-cell renal cell carcinoma (ccRCC) development." (PMID 36718277, 2023). "The cellular biology underlying the development of clear-cell renal cell carcinoma (ccRCC) usually involves the inactivation of VHL gene, which is required for normal cellular hypoxia response." (PMID 37506952, 2023). "Germline mutations in the VHL gene cause Von Hippel–Lindau disease, which associates with hemangioblastomas, clear cell renal cell carcinomas, and pheochromocytomas." (PMID 35163370, 2022). "Mutations in the Von Hippel–Lindau (VHL) gene are the driving force in many forms of clear cell renal cell carcinoma (ccRCC) and promote hypoxia-inducible factor (HIF)-dependent tumor proliferation, metastasis and angiogenesis." (PMID 35408930, 2022). "Germline loss-of-function mutations of the VHL tumor suppressor gene cause von Hippel–Lindau disease, which is associated with an increased risk of hemangioblastomas, clear cell renal cell carcinomas (ccRCCs), and paragangliomas." (PMID 36106637, 2022).
clear cell renal cell carcinoma (continued). "The association between the VHL gene and kidney cancer is widely recognized: it reaches a DisGeneNet association score of 0.9 and more than 90% of the renal clear cell carcinoma are known to be characterized by somatic mutations in the VHL gene." (PMID 35392801, 2022). "Clear Cell Renal Cell Carcinoma (ccRCC) are characterized by mutations that inactivate the von Hippel-Lindau (VHL) tumor suppressor gene and evidence indicated alterations in metabolic pathways, particularly in glutamine metabolism." (PMID 35223522, 2022). "VHL mutations were associated with the development of vascular tumors, such as renal clear cell carcinoma, pheochromocytoma, pancreatic neuroendocrine tumors, and central nervous system hemangioblastoma." (PMID 36506327, 2022). "Somatic alterations analysis of 354 ccRCC patients in TCGA Kidney Clear Cell Carcinoma (KIRC) dataset showed that 170 patients were with VHL mutations." (PMID 35624190, 2022). "VHL tumor suppressor gene inactivation is a hallmark of clear cell renal cell carcinoma (ccRCC), the most common form of kidney cancer, and promotes tumor growth by stabilizing the hypoxia-inducible factor 2 (HIF2) transcription factor." (PMID 35357972, 2022). "Inactive von Hippel-Lindau (VHL) is linked to metabolic reprogramming and plays pivotal roles in the pathogenesis of clear cell renal cell carcinoma (ccRCC)." (PMID 35637958, 2022). "A HIF-2 antagonist, belzutifan, was recently approved as a treatment option as it showed promising results in case of VHL mutated and clear cell renal carcinoma, and is currently being evaluated regarding PPGL treatment." (PMID 35163370, 2022). "In clear cell renal cell cancer (ccRCC), these pathways are constitutively active because of loss-of-function mutations of the VHL tumor suppressor gene, which forms part of the E3 ligase central to regulation of HIF." (PMID 36384128, 2022). "Most clear cell renal cell carcinomas (ccRCC) are associated with loss of von Hippel-Lindau tumor suppressor (pVHL) function and deregulation of the hypoxia pathway." (PMID 36364144, 2022). "A similar phenomenon has recently been reported in VHL‐deficient clear cell renal cell carcinoma where PHD3 silencing downregulated HIF‐2α mRNA stability." (PMID 35014036, 2022). "There are reports that the hypoxia pathway plays a crucial role in the development of many cancers including renal clear cell cancer, which has been stated to be VHL gene mutate." (PMID 34926261, 2021). "Mutation of the VHL gene, as found in clear cell renal carcinoma, leads to dysfunction of the VHL protein complex." (PMID 33466454, 2021). "In clear cell renal cell carcinoma, VHL loss-of-function mutations frequently leads to VHL deficiency and hence the upregulation of HIF-1α protein expression regardless of oxygen concentration." (PMID 34611473, 2021). "The majority of clear cell renal carcinoma (ccRCC) tumors are characterized by mutations of the VHL gene, encoding for VHL protein." (PMID 33466454, 2021). "Clear cell renal carcinoma (ccRCC), the most common type of kidney cancer, can be sporadic (frequently) or genetic (rare), both characterized by loss of the von Hippel-Lindau (VHL) gene that controls hypoxia inducible factors." (PMID 33803184, 2021). "For example, 9/11 BRAF V600E mutations were in melanoma samples, 9/10 KEAP1 mutations were in lung samples and 5/5 VHL mutations were in clear cell renal cancer samples." (PMID 34830758, 2021). "LOH at two loci (rs1642742 and rs1642743) of VHL gene results in a loss of VHL protein function, has been proposed as a candidate predictive biomarker for clinical outcome in clear-cell renal-cell carcinoma (ccRCC) patients." (PMID 33450833, 2021). "VHL deficient clear cell renal cell carcinomas (ccRCC) trigger the immune response resulting in cancer progression." (PMID 34563045, 2021). "Mutations in von Hippel-Lindau (VHL) play a critical role in developing clear-cell renal cell carcinoma (ccRCC)." (PMID 34257811, 2021).